HK2 (hexokinase 2)
Diseases named in the same sentence as HK2 in open-access papers (continued):
Sharing a sentence is not in itself a finding about the gene and the disease.
tumor (continued). "In vivo targeting was hK2-specific as verified by a 2.5-fold decrease in tumor uptake in pre-dosed xenografts or by a fourfold lower tumor accumulation in hK2-negative DU 145 xenografts." (PMID 26983637, 2016). "HK2, which is highly expressed in cancer cells, is thought to be required for tumor initiation and maintenance, and HK2 deletion is therapeutic in mouse models of cancer." (PMID 26576639, 2015). "Western blot analysis shows that HK2 level is significantly higher in cerebella with tumor in comparison to P7 whole cerebellum (p = 0.000012) and adult whole cerebellum (p = 0.000012)." (PMID 26192445, 2015). "Researchers have also linked biological markers of glycolysis (HK2, PFKFB4, PKM2, etc.)with tumor recurrence and OS in certain cancer patients." (PMID 26576639, 2015). "Glucose transporter 1 (GLUT1), HK2, ANGPTL4 and VEGF are well known downstream target genes of HIF-1 and are associated with tumor specific metabolic reprogramming, angiogenesis and metastasis." (PMID 25884381, 2015). "We also conducted IHC experiments of AKT2, AKT3, PKM2 and HK2 levels in xenograft tumor tissue sections." (PMID 26512921, 2015). "HKs are the first important irreversible enzymes of glycolysis, and the upregulation of mitochondria-bound HK2 in tumor cells promotes cell proliferation and escapes from mitochondria-associated cell death." (PMID 25938543, 2015). "HK2 is another molecule of interest in this regard, since HK2 has been shown to be specifically required for tumor initiation and maintenance in mouse models of cancer while being dispensable in adult mice without causing an overt phenotype." (PMID 25528771, 2015). "The upregulated mitochondria-bound HK2 in tumor cells, as well as the high glucose phosphorylation activity, promote tumor cell proliferation and survival by enhancing energy production and the escape from mitochondria-associated cell death." (PMID 25938543, 2015). "The tumour accumulation of 111In-DTPA-11B6 was hK2-specific, as verified by the low accumulation in the negative control, DU145 xenografts and by competitive binding assays using excess cold non-labelled antibody." (PMID 26116115, 2014). "Hk2 has long been known as a glycolytic enzyme, and has recently been proven to be involved in tumor or metabolic disorders or hypoxia-induced angiogenesis in these conditions." (PMID 23592914, 2013). "All three genes investigated, GLUT1, HK1, and HK2 as well as the normalizing gene β-actin were detected in all tumor and normal samples." (PMID 26824929, 2013). "In this study, tumor HK2 expression status identified a subset of patients with less favorable prognosis among patients with CKA-positive tumors." (PMID 23071593, 2012). "This study reports an interesting heterogeneity among patients with regards to tumor immunohistochemical expression of HK2 and CKA." (PMID 23071593, 2012). "Tumor HK2 expression was a weaker predictor of survival than tumor size and cancer stage in multivariable analysis." (PMID 23071593, 2012). "In turn, tumor CKA expression identified patients with worse prognosis among patients with HK2-positive tumors." (PMID 23071593, 2012). "Due to HK2’s reported role in promoting tumor growth we wanted to investigate if the tumorsuppressor function of miR-143 can in part be accounted for due to its down-regulation of HK2." (PMID 22691140, 2012). "HK2 is the first rate-limiting enzyme of glycolysis, conferring to the tumor an increased proliferation capacity and invasiveness when expressed at elevated levels." (PMID 23028787, 2012). "Antibody staining for HK2 was evident in 71 (45%) tumor specimens with moderate to high staining intensity in 23 (15%) of the samples." (PMID 23071593, 2012). "HK2 is often found upregulated in cancer and facilitates a high rate of glucose metabolism necessary for tumor growth." (PMID 22691140, 2012).
tumor (continued). "Within the top 20 genes ranked by Notch pathway-guided COCA, there are several genes related to differentiation (Tdgf1, Egr1 and Lefty1), cell growth (Ddit4, Hk2, Phlda2, Egln3 and Igfbp1) and tumor/cancer development (Afp, Sfrp2, Egr1, Hk2 and Phlda2)." (PMID 20353603, 2010). "All proteins were expressed in tumor cells, and expression was also seen in stroma cells for HK2, MEF2A, and MSN." (PMID 17054779, 2006). "In the tumour extracts, measurable hK2 and PSA concentrations were detected in 53% and 73% of cases respectively, and were positively correlated to each other (r = 0.59, P = 0.0001)." (PMID 10646889, 2000). "Silencing HK2 can enhance sorafenib sensitivity and suppress tumor growth in vivo." (PMID 40818043, 2026). "Beyond its role in glucose metabolism, HK2 promotes tumor survival by inhibiting apoptosis." (PMID 40818043, 2026). "While this study focuses on the role of HK2 in modulating T-cell metabolism and function, it is important to acknowledge that HK2 also plays a pivotal role in regulating the metabolic environment of tumor cells." (PMID 40181966, 2025). "3BP (HK2), a hexokinase II inhibitor, reduces adenosine triphosphate (ATP) levels and lactic acid production by inhibiting glycolysis, which promotes the polarization of tumor-related macrophages (TAMs) toward anti-tumor M1 phenotypes." (PMID 40033359, 2025). "The study found that PD-L1 enhanced glycolysis in NSCLC by upregulating HK2, which in turn may have a dampening effect on anti-tumor immunity." (PMID 40880642, 2025). "In addition, studies have found that PI3K/AKT signaling activation plays an important role in tumor aerobic glycolysis, which can regulate the activity and expression of some glycolytic enzymes such as HK2, PFK, and PK." (PMID 40045411, 2025). "In addition, analysis of tumor tissues revealed that NLRP12 promoted HK2 expression, histone lactylation, H3K18la, lactate levels and Myc transcription in vivo, all of which were reversed by sh-HK2 intervention." (PMID 40796546, 2025). "Finally, immunohistochemical analysis showed that HK2 protein was primarily localized in cytoplasm of tumor cells, and its expression was substantially downregulated following 2-DG treatment." (PMID 41415273, 2025). "Moreover, the IHC experiment found reduced expression of Ki67, p-Akt and HK2 in the tumor tissue of HCC827 combined with Daurisoline." (PMID 39699276, 2025). "Curcumin exerts broad-spectrum antitumor effects by precisely intervening in the glucose metabolism of tumor cells, notably by suppressing key glycolytic enzymes such as HK2, PKM2, and LDHA, as well as GLUT1 and MCTs, thereby effectively reversing the Warburg effect." (PMID 41515171, 2025). "Since ADAMTS9-AS2 suppressed OSCC cell proliferation, migration, and invasion, we explored whether the ADAMTS9-AS2/HK2 axis exerted its tumor-suppressive functions through glycolysis." (PMID 40831535, 2025). "Altogether, these findings may show the dispensability of HK2 in maintaining baseline immune responses but reveal its critical role in amplifying anti-tumor activity in environments with heightened metabolic demands." (PMID 40181966, 2025). "Furthermore, subsequent research demonstrated that miR-218 suppresses tumor growth and angiogenesis through the downregulation of HK2 and LDHA expression in vivo." (PMID 40661148, 2025). "Moreover, HK2 expression is critical for ADAMTS9-AS2/let-7a-5p axis-mediated tumor proliferation of OSCC cells." (PMID 40831535, 2025). "HK2 is a key enzyme in the glycolysis pathway that is overexpressed in cancer cells and is a promising target for cancer therapy due to its critical role in tumor growth and metastasis." (PMID 40243996, 2025). "Moreover, the IHC results confirmed that HK2 was consistently regulated by NAT10 in tumor xenograft tissues, organoids, and tissues of MNU-induced GC." (PMID 39990211, 2025).
tumor (continued). "However, HK2 expression is markedly upregulated in a wide range of malignant tumours, reflecting its dual regulation by insulin signalling and oncogenic drivers." (PMID 41586225, 2025). "Combined, this shows that HK2 may be a potent activator of glycolysis and tumor proliferation in GBM, making the enzyme a potential target in chemotherapies." (PMID 41450919, 2025). "Mechanistic and animal studies suggest RS may modulate tumor metabolism and inflammation by suppressing HK2-mediated glycolysis." (PMID 41415548, 2025). "HK2 is abundantly expressed in insulin‐sensitive regions such as cardiac, skeletal muscle, and adipose tissues, and its expression is also markedly elevated in highly oxygen‐consuming tissues, such as tumour tissues." (PMID 40415238, 2025). "Inhibiting HK2, which catalyses the first step of glycolysis, can disrupt glucose metabolism in cancer cells and promote better immune responses by reducing nutrient competition between immune cells and tumour cells." (PMID 40175681, 2025). "Knockdown of the HK2 gene in OC cells and ascites-derived tumor cells with the use of the glycolysis inhibitor 2-DG impeded lactate production, cell migration and invasion, and cell stemness properties, while decreasing FAK/ERK1/2 activation and metastasis and stemness-related genes." (PMID 40045411, 2025). "Indeed, ADAMTS9-AS2-mediated inhibition of tumor cell proliferation was reversed by the re-expression of HK2 in CAL27 and SCC9 cells." (PMID 40831535, 2025). "Therefore, HK2 is believed to be a key factor in promoting tumor growth and therefore stands out among the HK family and is currently the subject of extensive research." (PMID 39991762, 2025). "Therefore, HK2 not only plays a role in maintaining normal cell metabolism but also serves as a crucial factor in promoting tumor growth." (PMID 39991762, 2025). "P3H4 silencing suppresses tumor growth both in vitro and in vivo while simultaneously downregulating key glycolytic enzymes HK2 and LDHA, suggesting a potential metabolic vulnerability that could be therapeutically exploited." (PMID 41220593, 2025). "In contrast, by employing HK2 overexpression, we demonstrated that increased glycolytic flux significantly enhanced T-cell cytotoxicity, particularly in the nutrient-restricted and hypoxic conditions of the tumor microenvironment." (PMID 40181966, 2025). "As reduced glycolysis may impair T-cell function in the tumor microenvironment, we hypothesize that it may be possible to counter this by promoting glucose metabolism via the increased expression of HK2." (PMID 40181966, 2025). "As key enzymes, they all excellently characterize the glucose metabolism and thus the energetic situation of the tumor cell: GLUT-1 as the gateway into the cell, HK2 as the initiator of tumor-related metabolism and CAIX for pH stability as well as and for elimination of toxic waste products." (PMID 40535577, 2025). "Furthermore, when HK2 was silenced in combination with metformin, tumor cell growth was significantly suppressed, and mTORC1 inhibition occurred via an AMPK-independent mechanism." (PMID 40520908, 2025). "This suggests pre‐chemotherapy metabolic priming could sensitise MS_2 tumours: preclinical studies demonstrate that inhibiting glycolytic enzymes (e.g., HK2) or glutaminase restores NADPH pools and enhances doxorubicin response." (PMID 40457119, 2025). "HK2 degradation also reduces tumor cell motility, which contributes to the antimetastatic effect." (PMID 40998785, 2025). "Tumor-suppressive miRNAs converge on glycolysis by directly repressing rate-limiting nodes—HK2 (miR-125a/miR-885-5p), PFKFB3/GLUT1/c-Myc axis (miR-192-5p), and HIF-1α (miR-199a-5p/miR-3662), reducing glucose influx and lactate production and favoring mitochondrial oxidation." (PMID 41007803, 2025). "Furthermore, experimental knockout of HK2 in vivo resulted in significant decrease in tumor size, vasculature, and lactic acid." (PMID 41450919, 2025).
tumor (continued). "HK2, functioning as a glycolytic rate-limiting enzyme, demonstrates elevated expression in non-responsive patients, suggesting heightened glycolytic dependence consistent with the tumor Warburg effect." (PMID 41450464, 2025). "Furthermore, Zhimin Lu's et.al found HK2 activated the NF-κB pathway thus promoting PD-L1 expression and tumor immune escape by promoting phosphorylation and degradation of IκBα." (PMID 38479191, 2024). "2-DG is a small-molecule HK2 inhibitor that competitively inhibits HK2-mediated glucose phosphorylation, weakens the immunosuppressive network and macrophage polarization, enhances anti-tumor immunity, and contributes to local tumor control in mouse models." (PMID 39877360, 2024). "MiR-125a-5p suppresses LSCC by regulating HK2, which inhibits tumor growth." (PMID 39224810, 2024). "Furthermore, HK2's major function in controlling energy metabolism serves as the foundation for its control of tumour growth." (PMID 39661501, 2024). "Finally, it must be highlighted the possibility of using HK2peps in advanced or relapsing cancer stages, as HK2 induction characterizes chemoresistance in several tumor models and HK2 targeting in tumor cells sensitize them to chemo/radiotherapy." (PMID 38995012, 2024). "AST has been demonstrated to reduce the mRNA expression levels of c-Myc and glycolytic enzymes (LDH-A, Glut-1, and HK2) in a DSS-induced mouse model, suggesting its potential for combating tumor-associated inflammation and maintaining normal glucose homeostasis." (PMID 39330497, 2024). "HK2 is located at the core of the growth and survival process of tumour cells." (PMID 38288377, 2024). "In addition, tumor cells need to increase their efficiency by increasing glucose transporters, or various key enzymes, such as hexokinase 2 (HK2), pyruvate kinase M2 (PKM2), lactate dehydrogenase A (LDHA), aldolase C (ALDOC), alcohol dehydrogenase gene (ADH6)." (PMID 39438468, 2024). "Hexokinase 2 (HK2) upregulation is involved in the progression of LUAD, and it has been identified as an important metabolic function-associated marker for identifying circulating tumor cells in LUAD patient samples." (PMID 38041756, 2024). "HK2 was upregulated in GC tumor tissues according to the data in TCGA, GEPIA and ENCORI databases." (PMID 39054546, 2024). "Hypomethylation of the HK2 promoter leads to HK2 overexpression and tumor progression." (PMID 39119332, 2024). "Hexokinase 2 (HK2) is a crucial molecule that activates the glycolysis pathway of tumor cells." (PMID 38389923, 2024). "HK2 can promote glucose metabolism to meet the energy needs of tumour cells, inhibit the accumulation of ROS and Ca2+ in mitochondria, and increase the adaptability and survival of tumour cells." (PMID 38288377, 2024). "Human hexokinase 2 ( HK2 ) plays an important role in regulating Warburg effect, which metabolizes glucose to lactate acid even in the presence of ample oxygen and provides intermediate metabolites to support cancer cell proliferation and tumor growth." (PMID 38352584, 2024). "The anticancer potency of kaempferol was further confirmed in a mice xenograft model, revealing the ability to significantly prevent the growth of tumor size coupled with a marked decrease in hexokinase-2 expression and epidermal growth factor receptor (EGFR) activity in tumor tissues." (PMID 37216013, 2023). "In 2019, Nam reported that the gene signature related to DNA methylation differs between primary RCC and RCC metastases, as it was found, that metastatic tumours often demonstrated more pronounced changes compared to primary tumours, e.g., in metabolism-related HK2 and SZC16A3." (PMID 38003482, 2023). "Additionally, HK2 expression in cancers is stimulated by the insulin signaling pathway Akt/mTORC1, which is upregulated in tumor cells to regulate glucose metabolism, cellular growth, and survival through the phosphorylation of target molecules." (PMID 37109475, 2023).
tumor (continued). "Consequently, targeting glycolysis in tumor cells represents a novel and promising therapeutic approach.The rate-limiting step in glycolysis is regulated by a collection of enzymes, such as HK2, PK." (PMID 38099309, 2023). "In addition to its enzymatic activity, the mitochondrial binding ability of HK2 plays a role in inhibiting apoptosis and upregulating synthetic pathways which support tumor growth." (PMID 37109475, 2023). "In addition, miR-216b is considered as a tumor suppressor that can directly downregulate HK2, block mTOR signaling pathway, and induce autophagy and apoptosis in cancer cells." (PMID 37204526, 2023). "Besides, when glycolysis in cellular metabolism is exuberant, HK2 can phosphorylate IκBa in tumor cells, leading to IκBa degradation and NF-κB activation-dependent increase in PD-L1 expression to evade tumor immunity." (PMID 37234166, 2023). "In contrast, the knockdown of HK2 in HK1- HK2+ cancers reduced xenograft tumor progression." (PMID 37109475, 2023). "In addition, the glycolysis driven by hexokinase 2 (HK2) is increased in tumor PCs, and which up-regulates their ROCK2-MLC2 mediated contractility leading to impaired blood vessel supporting function." (PMID 37666813, 2023). "Other studies showed that the deletion of HK2 could impair the tumorigenicity of tumor cells, thus restoring their sensitivity to radio/chemotherapy." (PMID 37779163, 2023). "They found that siRNA@ABMBP-COF could induce ferroptosis and apoptosis in HT1080 fibrosarcoma cells by downregulating SLC7A11 and HK2, suggesting the significant anti-tumor capacity in a tumor-bearing nude mouse model." (PMID 36819098, 2023). "The results also suggested that gastrodin could suppress HK2-mediated glycolysis and tumor progression in OSCC." (PMID 37779163, 2023). "Previous studies demonstrated that HK2 overexpression could promote the growth and immortalization of tumor cells via regulating glucose metabolism." (PMID 37779163, 2023). "There was convincing evidence that WTAP could widely affect the Warburg effect by targeting HK2 in various tumor cells." (PMID 37297015, 2023). "Therefore, the HK2 catalysis of glucose can be guaranteed; thus, the catalytic efficiency of HK2 is improved, and the proliferation of tumor cells is promoted." (PMID 36994237, 2023). "Further tumor lactate analysis verified that let-7b-5p regulated lactate production via HK2." (PMID 37019900, 2023). "Moreover, HK2, MMP11, CDH3, PDK4, SERPINB5, and SLC2A1 expression were closely associated with tumour stages." (PMID 37234801, 2023). "In the first aspect, the metabolic activity of HK2, as a glucokinase, could play a vital role in immune escape and resistance to radio/chemotherapy (cisplatin, paclitaxel) during tumorigenesis and tumor development." (PMID 37779163, 2023). "We also found that HK2 silencing suppressed tumor growth in vivo." (PMID 37854321, 2023). "In a hepatocarcinogenesis mice model, liver-specific depletion of HK2 decreased tumor incidence." (PMID 37524692, 2023). "The expression of HK2, the prevalent isoform in HCC, is associated with reduced survival in HCC patients, and, accordingly, HK2 inhibition dampens glycolysis in favor of OXPHOS, relieving the tumor phenotype." (PMID 36835122, 2023). "Furthermore, accumulating evidence has suggested that targeted inhibition of HK2 or HK2 downregulation can inhibit tumor growth and restore the sensitivity of tumor cells to therapy." (PMID 37779163, 2023).